INS (insulin)
Diseases named in the same sentence as INS in open-access papers (continued):
Sharing a sentence is not in itself a finding about the gene and the disease.
diabetes (continued). "In the case of whey protein, some studies report positive effects, such as improvements in postprandial glycemia, insulin secretion, and insulin resistance, particularly in well-controlled type 2 diabetes or overweight individuals at risk for diabetes." (PMID 40075050, 2025). "For diabetes, zinc’s involvement in glucose metabolism and insulin regulation can help reduce inflammatory markers associated with the disease, potentially aiding in glycemic control and protecting against diabetes-related complications." (PMID 40390089, 2025). "Diabetes is a metabolic disease characterized by chronic hyperglycemia caused by multiple etiologies, generally related to impaired insulin secretion and insulin resistance." (PMID 40801711, 2025). "Numerous studies have linked reduced QoL to age, diabetes duration, insulin use, obesity, and DM-related complications." (PMID 41010974, 2025). "Overt hypercortisolism or long-term exposure to exogenous glucocorticoids are linked to an elevated risk of type 2 diabetes mellitus, as well as insulin resistance via reducing insulin action and decreasing glucose disposal." (PMID 40806839, 2025). "In this study, we evaluate possible impairments in the overall incretin secretion from normal glucose tolerance to overt diabetes, as well as their association with impaired insulin secretion." (PMID 40354158, 2025). "On the other hand, type 2 diabetes mellitus (T2DM) can be caused by either insufficient insulin production or insulin resistance." (PMID 40937409, 2025). "According to the outcomes of the animal studies, each study demonstrates that gene therapy can increase insulin production, maintain stability, and decrease complications caused by diabetes mellitus." (PMID 39858654, 2025). "The underlying mechanism of stone formation in patients with diabetes and obesity is the production of excess uric acid in the urine due to insulin resistance and increased fatty acid production, which in turn leads to the formation of uric acid stones." (PMID 40061424, 2025). "According to American Diabetes Association Professional Practice Committee, once insulin therapy is started, a target glucose range of 7.8–10.0 mmol/L is recommended for the majority of critically ill and noncritically ill patients." (PMID 40568192, 2025). "Women generally have higher body fat percentages and different fat distribution patterns compared to men, which can influence insulin sensitivity and inflammatory responses associated with diabetes." (PMID 40756518, 2025). "Mutations within the insulin B-chain, such as G(B20)R and P(B28)L, generally lead to milder forms of diabetes." (PMID 40305339, 2025). "Diabetes, primarily type 2 (95% of cases), is a chronic disease linked to abnormal insulin function and poses a significant global health threat." (PMID 40860483, 2025). "Extensive skeletal muscle FDG accumulation can be caused by diabetes (also in suspected cases of diabetes), administration of insulin, and the presence of gastric food residue, even if fasting for at least 4 h before FDG administration." (PMID 39412643, 2025). "Methylation changes in immune-related genes (e.g., TXNIP, ABCG1) have been associated with inflammatory pathways, insulin signaling, and glucose metabolism, thereby contributing to diabetes progression." (PMID 40380284, 2025). "Type 2 diabetes mellitus (T2DM) results in the loss of the ability of insulin to act on insulin receptors." (PMID 41373306, 2025). "Zinc deficiency constitutes a significant risk factor for diabetes, given its essential role as a cofactor in the synthesis, storage, and secretion of insulin by the pancreas." (PMID 40647294, 2025). "High basal insulin secretion rate (BasalISR) was identified as the primary causal driver of liver fat accumulation in both diabetes and non-diabetes." (PMID 40502600, 2025).
diabetes (continued). "T2DM is the most prevalent form of diabetes mellitus (DM), a chronic disease characterized by hyperglycemia due to secretion deficiencies and resistance to insulin." (PMID 41007804, 2025). "Mechanistically, compromised insulin secretion underlies this transgenerational susceptibility to diabetes." (PMID 39934105, 2025). "The keywords of cluster 2 (green) are mainly about the research of progression, inflammation, diabetes, renal injury, insulin, deficiency, blood pressure, complication, model, macrophage, risk, streptozotocin, system, therapy, obesity." (PMID 40862124, 2025). "Diabetes is a disease associated with an increase in the glucagon/insulin ratio in terms of the biological activity of these two hormones, and hence with an increase in cellular levels of cAMP and a decrease in cellular levels of succinyl-CoA." (PMID 40305364, 2025). "Early lifestyle changes have been shown to result in significant weight loss, improved insulin sensitivity, and reduced waist circumference, making them effective in preventing diabetes among at-risk adults." (PMID 41257676, 2025). "Insulin resistance plays a significant role in muscle atrophy in diabetes mellitus, causing abnormal insulin signaling by reducing tyrosine phosphorylation of the insulin receptor and phosphorylation of Akt." (PMID 38916919, 2025). "Diabetes, as a global chronic disease among millions of people, is caused by the inability to produce insulin because of pancreatic dysfunction (type 1 diabetes) or caused by the malfunction of cells to use insulin (type 2 diabetes)." (PMID 41144543, 2025). "This MR study establishes a causal connection between the use of insulin and an elevated risk of OA, with diabetes and smoking acting as significant mediators." (PMID 41398760, 2025). "Diabetes mellitus is a chronic condition marked by high blood glucose levels caused by the dysfunction and/or death of pancreatic insulin-secreting β cells." (PMID 41480350, 2025). "Diabetes distress is common and strongly associated with younger age at diabetes onset, insulin use, foot ulcer, and anxiety and depression symptoms." (PMID 39972441, 2025). "The cumulative effect of the LoF was associated with diabetes, reduced insulin secretion, and higher levels of GH and IGF-1." (PMID 39137152, 2025). "Additional site-level factors—such as staffing ratios, diabetes team involvement, and differences in insulin titration protocols and baseline hypoglycemia risk—further reduced comparability across studies." (PMID 41517284, 2025). "Immunostaining of pancreatic islets demonstrated that Car@PLGA-NPs effectively reversed diabetes-associated hormonal dysregulation: significantly increasing depleted insulin levels and decreasing elevated glucagon levels in db/db mice (P < 0.001)." (PMID 41586316, 2025). "By incorporating data from approximately 2,047,256 patients across multiple studies, our findings suggest a potential reduction in CRC risk associated with GLP‐1RAs when compared with traditional diabetes therapies such as insulin and TZDs." (PMID 39980820, 2025). "Diabetes mellitus is a chronic condition caused by the body’s resistance to insulin, which leads to disturbances in maintaining glucose balance and can result in blood sugar fluctuations and complications related to blood vessels." (PMID 41011114, 2025). "Diabetes mellitus encompasses a group of metabolic disorders characterized by hyperglycemia due to either relative or absolute deficiency of insulin hormone." (PMID 40034631, 2025). "PUE was found to improve lipid metabolism disorders caused by insulin dysfunction, regulate blood lipid levels in diabetic mice, and mitigate damage caused by type 2 diabetes mellitus." (PMID 40336535, 2025). "Type 2 diabetes mellitus is associated with insulin resistance of peripheral tissues and cells and increased blood glucose levels (hyperglycemia)." (PMID 39859258, 2025).
diabetes (continued). "How is global disparity in access to diabetes technologies and insulin associated with glycemic outcomes in children with type 1 diabetes (T1D)?" (PMID 40864470, 2025). "Diabetes is a metabolic disease marked by prolonged high glucose levels in the bloodstream caused by insufficient insulin production or compromised insulin function, which can be attributed to poor pancreatic β-cell activity or insulin resistance." (PMID 40143098, 2025). "Type 2 diabetes mellitus (DM2) is a metabolic disorder characterized by chronic hyperglycemia associated with low insulin production and/or insulin resistance." (PMID 40426986, 2025). "While organotins have been shown to cause diabetes by reducing insulin secretion in animal studies, there are insufficient epidemiological studies on this topic." (PMID 41488239, 2025). "On this basis, the American Diabetes Association recommends combining GLP-1 RAs with insulin to improve treatment efficacy, sustain long-term benefits, and reduce cardiovascular risk." (PMID 41011236, 2025). "Administration of exogenous insulin is required to maintain glycemic control for individuals afflicted with severe insulin‐deficient and insulin‐resistant subtypes of diabetes mellitus." (PMID 38877295, 2025). "It was aspects of their diabetes care and insulin management that had caused distress during their admission." (PMID 41358572, 2025). "Disruptions in the GLUT-4 function in muscles or adipose tissue impair insulin-mediated glucose uptake, contributing to insulin resistance and increasing the risk of diabetes development." (PMID 40429763, 2025). "These SNPs were related to the risk of GDM, type 2 diabetes mellitus, and/or reduced insulin sensitivity in other studies as well." (PMID 41003098, 2025). "Phosphorylated Fet A can inhibit insulin signal transduction by binding to the β-subunit of the insulin receptor, thus causing insulin resistance in type 2 diabetes mellitus." (PMID 39790934, 2025). "Analyzing diabetes‐related hormones such as insulin and glucagon using conventional enzyme‐linked immunosorbent assay (ELISA) has been the gold standard." (PMID 40278502, 2025). "Epidemiological studies suggest that RPA reduces the risk of developing depression in those with diabetes by enhancing insulin sensitivity and glucose uptake, improving cardiovascular fitness and blood pressure regulation, and decreasing inflammation." (PMID 41004502, 2025). "Diabetes affects >10% of adults worldwide and is caused by impaired production or response to insulin, resulting in chronic hyperglycemia." (PMID 40982369, 2025). "Previously reported risk factors for falls in persons with diabetes include diabetic neuropathy, diabetic retinopathy, elevated cystatin C levels, insulin or sulfonylurea use, and decreased grip strength, knee extension, and ankle dorsiflexor muscle strength." (PMID 40097434, 2025). "In a rodent study, PP-sterically stabilized micelles (SSM) improved glucose tolerance and insulin sensitivity in rats with pancreatogenic diabetes caused by pancreatic diseases like chronic pancreatitis and pancreatic neoplasia." (PMID 40214973, 2025). "This cross-sectional study estimates the association of accessibility and reimbursement for diabetes technologies and insulin with glycemic control among children with type 1 diabetes using data from the global SWEET Study dataset." (PMID 40864470, 2025). "For example, heavy drinking has been shown to increase the risk of diabetes due to the direct toxic effect of alcohol on pancreatic islet cells, inhibiting insulin secretion and increasing insulin resistance." (PMID 40342576, 2025). "A mediation analysis showed that white blood cell count (WBC) and neutrophil count partially mediate the association between diabetes-related markers (glycated hemoglobin, fasting blood glucose, and insulin) and OAB." (PMID 40475997, 2025).
diabetes (continued). "In T1D, ectopic lipid accumulation and MASLD development can result from obesity or altered insulin kinetics representing another independent risk factor for diabetes-related complications." (PMID 39998445, 2025). "Both the HD–LA group and the group with RAD values below the 25th percentile had a higher risk of diabetes compared with their respective reference groups when using the insulin demand–adequacy method and the RAD method, respectively." (PMID 39611962, 2025). "Dysregulation of miRNAs from insulin-sensitive organs or tissues have been implicated in the pathogenesis of diabetes and insulin resistance." (PMID 41002956, 2025). "When replacing standard insulin autoantibodies (IAA) with oxPTM-INS-Ab diabetes risk increased to 100% in children with oxPTM-INS-Ab+ in combination with autoantibodies to GAD (GADA) and IA-2 (IA-2A), compared to 84.37% in those with IAA/GADA/IA-2A (p=0.04)." (PMID 40028329, 2025). "Type 2 diabetes mellitus (T2D) is characterized by a progressive and uneven loss of insulin secretion from pancreatic β-cells, often following insulin resistance (IR)." (PMID 41157089, 2025). "Metformin is a commonly used first-line drug in type 2 diabetes and should also be used in diabetes associated with acromegaly as it improves insulin sensitivity." (PMID 40142714, 2025). "This study found that elevated AIP significantly raises the risk of diabetes in hypertensive patients, likely due to hypertension-induced oxidative stress and inflammation impairing insulin signaling." (PMID 40130162, 2025). "Diabetes is a group of metabolic disorders caused by abnormal carbohydrate metabolism, insufficient insulin production, and/or insulin resistance resulting from environmental and genetic components." (PMID 40019178, 2025). "Inactivating mutations can cause excessive insulin secretion, resulting in congenital hyperinsulinemia, whereas activating mutations can lead to diabetes." (PMID 40650956, 2025). "Because intracellular serotonin regulates insulin secretion from pancreatic β cells through serotonylation of Rab3a and Rab27a, mice selectively deficient in serotonin develop diabetes." (PMID 39926388, 2025). "In the liver, MetR has a profound effect on lipid and glucose metabolism, resulting in increased insulin sensitivity and reduced risk of diabetes mellitus and hypertension." (PMID 40723841, 2025). "In T2DM, the glucose variability, a known contributor to diabetes complications, was associated with MAPK1 through its role in insulin secretion, glucose metabolism, and glycogen biosynthesis, emphasizing its central position in diabetes‐related gene networks." (PMID 40823947, 2025). "Diabetes mellitus is characterised by chronically elevated blood glucose levels due to the insufficient insulin production caused by an autoimmune destruction of pancreatic beta cells (β-cells) and insufficient insulin utilisation by the body." (PMID 40142900, 2025). "It contributes to liver health by slowing hepatocellular carcinoma (HCC) progression, improves metabolic health by enhancing insulin sensitivity and reducing diabetes risk, and lowers inflammation by reducing oxidative stress and cytokines like IL-6 and TNF-α." (PMID 40718363, 2025). "Compared with standard enteral nutrition formulas, diabetes-specific formulas demonstrated significant advantages in lowering blood glucose levels, reducing insulin requirements, and decreasing the risk of acquired infections." (PMID 39940308, 2025). "In diabetes, impaired insulin function can cause abnormally high lactate levels, especially after a glucose load, highlighting altered metabolic processes." (PMID 40742490, 2025). "These mice develop mild diabetes due to impaired insulin secretion caused by disruption in pancreatic β cells, without the obesity or leptin deficiencies other genetic mouse models have been found to develop." (PMID 40565059, 2025).
diabetes (continued). "Overexpression of MUC1 in endometrial cells, particularly in patients with diabetes, has been linked to insulin and is associated with fertility issues." (PMID 39996906, 2025). "Hyperglycemia is a characteristic of diabetes mellitus, a chronic disease, leading to lipid, carbohydrate, and protein metabolic abnormalities caused by insulin insensitivity." (PMID 41368517, 2025). "Diabetes mellitus, a metabolic disorder, arises from insulin secretion deficiency or insulin dysfunction." (PMID 39950114, 2025). "Diabetes mellitus is a growing global health concern, characterized by chronic hyperglycemia due to absolute or relative deficiencies in insulin production or action." (PMID 41516077, 2025). "Mitochondrial DNA (mtDNA) variants considerably affect diabetes mellitus by disturbing mitochondrial function, energy metabolism, oxidative stress response, and even insulin secretion." (PMID 39835172, 2025). "Several oral diabetes agents are known to promote the secretion of insulin in the pancreas, but they can cause hypoglycemia." (PMID 39899133, 2025). "This type of exercise can improve insulin sensitivity, manage metabolic stress, and potentially influence myonectin levels favorably, especially in populations at risk for diabetes or with existing insulin resistance." (PMID 40134450, 2025). "Regular follow-up allowed for continuous insulin adjustments as the patient's needs evolved, particularly given the long-term nature of diabetes associated with PTF1A mutations." (PMID 40443916, 2025). "In our view, it is in diabetic subjects that the measurement of insulin or C-peptide has the greatest value, and this approach has now been emphasized by the American Diabetes Association." (PMID 40218874, 2025). "Our data suggest that PTP1B deficiency enhances insulin signaling in the conditions of hypoinsulinemic diabetes and eNOS deficiency, increases adaptive sXBP-1 signaling, reduces maladaptive CHOP expression, and attenuates diabetic podocyte injury in vivo." (PMID 40027018, 2025). "WS‐associated diabetes is a non‐autoimmune, insulin‐dependent diabetes mellitus that typically manifests before 6 years of age and is mainly treated with insulin." (PMID 40641032, 2025). "Panova and colleagues used iPSCs from a patient diagnosed with neonatal diabetes mellitus carrying the INS mutation in the second intron (c.188-31G>A) and engineered isogenic CRISPR/Cas9 mutation-corrected cell lines." (PMID 40943666, 2025). "Diabetes is a metabolic disease characterized by hyperglycemia, primarily caused by defective insulin secretion or impaired insulin action." (PMID 40766763, 2025). "This study investigated changes in the risk of diabetes, β-cell function, and insulin sensitivity during the menopausal phase, considering the timing of diabetes onset." (PMID 40361840, 2025). "These candidate genes were primarily associated with insulin/glucose/lipid metabolism and the pathogenesis of diabetes, which are all closely related to the development of ketosis." (PMID 41010281, 2025). "Type 1 diabetes (T1D) is generally viewed as an etiologic subtype of diabetes caused by the autoimmune destruction of the insulin-secreting β-cells." (PMID 40244115, 2025). "Diabetes mellitus is a chronic common disease, caused either by insufficient production of insulin by the pancreas or by ineffective use of insulin produced by the body." (PMID 40104114, 2025). "Diabetes commonly co-occurs with disruptions in lipid and protein metabolism, with lipid metabolism intricately linked to insulin and glucose regulation in the body." (PMID 40565724, 2025). "Chronic hypokalemia and hypomagnesemia in this syndrome can hinder glucose metabolism, insulin sensitivity, and secretion in diabetic patients, which can predispose them to brittle diabetes with microvascular complications, as observed in our patient." (PMID 40520344, 2025).